TRAP1 (TNF receptor associated protein 1)
Diseases named in the same sentence as TRAP1 in open-access papers (continued):
Sharing a sentence is not in itself a finding about the gene and the disease.
osteosarcoma (9 papers, 2013 to 2023). A usually aggressive malignant bone-forming mesenchymal neoplasm, predominantly affecting adolescents and young adults. "It is postulated that TRAP1/HSP75 overexpression inhibits oxidative stress induced Saos-2 osteosarcoma cells death by inducing the levels of reduced glutathione." (PMID 34107382, 2021). "Accordingly, we found that knocking-down TRAP1 expression in human osteosarcoma SAOS-2 cells and human cervix carcinoma HeLa cells (cells expressing short hairpin TRAP1 RNAs were dubbed shTRAP1), caused a constitutive increase in the levels of intracellular ROS and of mitochondrial superoxide anion." (PMID 25564869, 2014). "These RBPs include NOP58, FAM120C, DYNC1H1, TRAP1, and LMNA, which may serve as molecular targets for osteosarcoma immune regulation." (PMID 37139238, 2023).
glioma (8 papers, 2012 to 2023). A benign or malignant brain and spinal cord tumor that arises from glial cells (astrocytes, oligodendrocytes, ependymal cells). "Since active scavenging of ROS is associated with glioma stem cell resistance to radiation and chemotherapy, the interplay between TRAP1 and SIRT3 may contribute to the therapeutic resistance of cancer stem cells in vivo." (PMID 31947673, 2020). "Supplementing growth media with recombinant HOP protein stimulated proliferation in glioma cells and effect dependent on activation of TRAP1/AKT and MAPK/PI3K signaling." (PMID 34831344, 2021). "Inhibition of either TRAP1 or SIRT3 in glioma stem cells leads to metabolic dysregulation, overproduction of ROS, loss of stemness properties, and cell death both in vitro and in vivo." (PMID 31947673, 2020). "Conversely, recent evidence suggests that post-transcriptional S-nitrosylasion and acetylation mechanisms are responsible for TRAP1 modulation in, respectively, hepatocellular carcinoma and glioma cells." (PMID 31878280, 2019). "In addition, TRAP-1 is expressed more highly in glioma stem cells than in their differentiated counterparts, and TRAP-1 activation promotes cellular metabolism via mitochondrial respiration, which is required for survival under low glucose conditions." (PMID 35269393, 2022). "Furthermore, it has been recently proposed that TRAP1 is acetylated upon interaction with sirtuin-3 in mitochondria of glioma cells." (PMID 31878280, 2019). "TRAP1 protects mitochondrial integrity and prevents apoptosis, thus induces the resistance to temozolomide (TMZ), the standard chemotherapy drug for glioma." (PMID 38098505, 2023). "An interaction between TRAP1 and SIRT3 has been reported in glioma stem cells (GSC), where the two proteins reciprocally sustain their activities: SIRT3-mediated deacetylation maintains TRAP1 chaperone activity, which in turn stabilizes SIRT3." (PMID 35959462, 2022). "Similar results were obtained by transient knockdown of TRAP1 in two different cell lines, SH-SY5Y neuroblastoma cells and KNS-42 glioma cells." (PMID 23284813, 2012). "In complementary experiments, knockdown of HOP reduced glioma cell proliferation and increased apoptosis; additionally, analysis of 153 glioblastoma patient samples revealed a positive correlation between HOP and TRAP1 expression." (PMID 34831344, 2021). "Very recently, it has been shown that SIRT3 and TRAP1 are overexpressed in glioma stem cells, and that the interplay between them increases activity of the ETC without increasing the ROS concentration in glioma stem cells mitochondria." (PMID 31947673, 2020).
hepatocellular carcinoma (8 papers, 2017 to 2025). A malignant tumor that arises from hepatocytes. "TRAP1’s function in hepatocellular carcinoma cell invasion, migration, and proliferation was examined in vitro using wound healing assays and the cell counting kit-8; apoptosis was examined through reactive oxygen species detection." (PMID 41422190, 2025). "Further in vitro experiments demonstrate that knocking down TRAP1 significantly suppresses malignant phenotypes of tumor cells in hepatocellular carcinoma by inducing oxidative stress and apoptosis." (PMID 41422190, 2025). "In contrast to these inhibitory effects, the SNO of Cys501 of the mitochondrial chaperone TRAP1 in hepatocellular carcinoma cells was shown to promote TRAP1 degradation, thereby increasing succinate dehydrogenase (SDH) levels and activity." (PMID 38739938, 2024). "TRAP1 is highly expressed in many types of human tumors, including breast cancer, hepatocellular carcinoma (HCC), and glioblastoma." (PMID 37351538, 2023). "In such a perspective, a recent study demonstrated that S-nitrosylation is a major posttranslational modification responsible for regulation of TRAP1 expression in hepatocellular carcinoma." (PMID 28177905, 2017). "The upregulation of TRAP1 occurs before the development of cancerous changes and is observed only in lesions that progress to carcinoma in colorectal cancer associated with ulcerative colitis and in a specific animal model of hepatocellular carcinoma (HCC) progression." (PMID 38802732, 2024). "This is because TRAP1 is found to be significantly expressed in groups of patients with hepatocellular carcinoma (HCC)." (PMID 38802732, 2024). "Moreover, it has been reported that GSNOR-downregulating hepatocellular carcinoma (HCC) cells show reduced levels of TRAP1." (PMID 32411008, 2020).
cervix carcinoma (5 papers, 2014 to 2023). "However, levels of TRAP1 expression also suggest an onco-suppressive role, as its expression levels are decreased in certain types of tumors, such as ovarian, renal, and cervical carcinomas." (PMID 37508418, 2023).
non-small cell lung carcinoma (5 papers, 2015 to 2023). A group of at least three distinct histological types of lung cancer, including non-small cell squamous cell carcinoma, adenocarcinoma, and large cell carcinoma. "In addition, high -TRAP1 expression level was also associated with increased risk of disease recurrence in non-small cell lung cancer." (PMID 28088229, 2017). "The expression of Trap1 has been found upregulated in various human malignancies, including nasopharyngeal, breast, prostate, and non-small cell lung cancer leading to reduced apoptosis." (PMID 34769067, 2021). "TRAP1 knockdown reduced cell growth and clonogenic cell survival and impaired mitochondrial function in non-small cell lung cancer cells." (PMID 29621137, 2018).
breast tumors (4 papers, 2015 to 2022). "One of the genes from module 1 is TRAP1, whose overexpression is involved in promoting breast tumor growth." (PMID 36371461, 2022). "In this study, we showed that TRAP1 is aberrantly upregulated in breast tumors compared to control tissues." (PMID 26517089, 2015). "Some studies believe that some HSP90 family genes such as HSP90AA1 and TRAP1 are not necessary for breast tumors to develop and metastasize; however, they have surprising regulatory effects." (PMID 34109171, 2021).
colorectal tumors (4 papers, 2011 to 2021). "The analysis of TCGA database showed that a subgroup of colorectal tumors is characterized by gain/loss of TRAP1 copy number, this correlating with its mRNA and protein expression." (PMID 28177905, 2017). "A study on colorectal tumors found a positive correlation between TRAP1 and BRAF levels." (PMID 34831420, 2021). "Furthermore, the study found that TRAP1/HSP90 inhibitors led to a decrease in BRAF, with this effect appearing more pronounced in colorectal tumor cell lines with the BRAFV600E mutation, suggesting that TRAP1 plays a key role in maintaining BRAF expression." (PMID 34831420, 2021). "In conclusion, this study provides the first comprehensive proteomic evaluation of TRAP1 protein network in colorectal tumors, showing the clinical relevance of its activation as a mechanism to coordinate a number of signaling pathway responsible for tumor progression and clinical aggressiveness." (PMID 28177905, 2017). "Indeed, TRAP1 gene CN may represent a surrogate marker of its expression in colorectal tumors and correlate with lymph node involvement in a large cohort of human CRCs and thus deserves to be evaluated as a reliable diagnostic/prognostic tool for clinical use." (PMID 31878280, 2019). "However, there is a subgroup of human CRCs characterized by TRAP1 protein upregulation independently from gene CN variation and mRNA expression, suggesting that post-transductional mechanisms are also likely to play a role in regulating TRAP1 expression in colorectal tumors." (PMID 31878280, 2019).
esophageal squamous cell carcinoma (4 papers, 2015 to 2020). Esophageal squamous cell carcinoma (ESCC) is a type of esophageal carcinoma (EC) that can affect any part of the esophagus, but is usually located in the upper or middle third. "In agreement with our results, Trap1 appears to promote cell migration and invasion in human esophageal squamous cell cancer." (PMID 28407697, 2017).
lymph node metastasis (4 papers, 2017 to 2024). "Although elevated TRAP1 levels are associated with a negative prognosis, strong TRAP1 expression is correlated with a higher chance of lymph node metastasis." (PMID 38802732, 2024). "However, researchers have already observed that TRAP1 was significantly upregulated in CRC patients with lymph node metastasis compared to those without LM metastasis." (PMID 33228590, 2020).
melanoma (4 papers, 2017 to 2025). A malignant, usually aggressive tumor composed of atypical, neoplastic melanocytes. "Because of its importance in maintaining mitochondrial protein folding integrity as a chaperone, TRAP1 inhibition in a study led to decreased oxidative phosphorylation and glycolysis in multiple cancer cell lines, including melanoma cell lines." (PMID 34831420, 2021). "Given the metabolic plasticity of melanoma, further research can help determine what metabolic profile would be most vulnerable to TRAP1 inhibitory treatment." (PMID 34831420, 2021).
Obesity (4 papers, 2018 to 2025). Accumulation of substantial excess body fat. "Five differentially methylated regions were in genes previously found to be associated with obesity and altered metabolic states (TRAP1, SLC38A3, PROX1, ALDH1B1, and FAM96A)." (PMID 36474183, 2022). "In these studies mRNA expression of Hsp90ab1, Hsp90aa1, Hsp90b1, and TRAP1 were assessed from skeletal muscles of mice fed a high fat diet (diet-induced obesity, DIO) and compared to lean counterparts." (PMID 29434648, 2018). "Of these genes, four (TRAP1, SLC38A3, PROX1, and FAM96A) have also been associated with obesity and altered metabolic states, indicating that they may be implicated in differential progression of lean versus obese NASH-HCC." (PMID 36474183, 2022). "On the other hand, monocytes from mothers with obesity (n = 3/time point) exhibited suppression of genes involved in interferon signaling (STAT1, GBP5, PSMB8) and response to reactive oxygen species (STRBP, HEBP2, TRAP1, TRPA1) (p value <0.001) with gestational age." (PMID 34195568, 2021).
renal carcinoma (4 papers, 2017 to 2024). A carcinoma arising from the epithelium of the renal parenchyma or the renal pelvis. "However, TRAP1 is also downregulated in specific tumors, such as ovarian, bladder and renal cancers, where its lower expression is correlated with the worst prognoses and chemoresistance." (PMID 29621137, 2018). "Therefore, human malignancies with high TRAP1 level, including CRC, are characterized by a predominant glycolytic phenotype, whereas other human neoplasms characterized by low TRAP1 expression (i.e. ovarian, cervical and renal carcinomas) exhibit a predominant oxidative metabolism." (PMID 39210159, 2024).
renal fibrosis (4 papers, 2018 to 2024). A final common manifestation of a wide variety of chronic kidney diseases characterized by glomerulosclerosis and tubulointerstitial fibrosis. "Hence, it has been proposed that TRAP1 safeguards the mitochondria against damage in models of renal fibrosis, and a proband with thyroid and kidney malignancies was found to have a TRAP1 mutation." (PMID 38802732, 2024). "In addition, overexpression of Trap1 can attenuate UUO-induced renal fibrosis and maintain mitochondrial integrity; however, the underlying mechanism is still unclear." (PMID 35765067, 2022).
brain Tumors (3 papers, 2019 to 2024). "It is acknowledged that these signaling pathways might interact and enhance each other since both TRAP1 and c-Myc are simultaneously up-regulated in brain tumor-initiating cells." (PMID 31181660, 2019). "Besides, five additional inputs were found after searching for alterations in BCOR, BCORL1, EP300, TRAP1, CREBBP, and L3MBTL2 in the repository of 23 published studies on neuroepithelial brain Tumors including 7207 samples of 6761 patients." (PMID 38637838, 2024). "However, TRAP1 (HSP75), DNAJA3 (TID1), and DNAJC19 remain to be extensively explored in brain tumors regarding their roles in angiogenic dormancy." (PMID 38994941, 2024).
clear cell renal cell carcinoma (3 papers, 2020 to 2024). "Study has shown that when the expression level of TRAP1 decreased, the invasiveness of colon and renal clear cell carcinoma cells and the production of reactive oxygen species (ROS) increased." (PMID 38880903, 2024).
gastric cancer (3 papers, 2023 to 2025). A primary or metastatic malignant neoplasm involving the stomach. "drugs, particularly in stomach cancer, where TRAP1 expression is significantly correlated with resistance to 44% of the drugs in this category." (PMID 37508418, 2023). "Nevertheless, no more targeted drugs are developed for TRAP1 in gastric cancer until now, and the therapeutic field for gastric cancer targeting mtHsp90 remains blank." (PMID 38098505, 2023). "In addition, TRAP1 may regulate the malignant biology of cells by increasing the expression of CyclinB1, CyclinD1, CyclinE, MMP-2, and VEGF, leading to the development and progression of gastric cancer, which is an important target for targeted therapy." (PMID 38098505, 2023).
liver cancer (3 papers, 2021 to 2025). An epithelial or non-epithelial malignant neoplasm that arises from the liver. "It is possible that the expression of TRAP1 is associated with autophagy in liver cancer; HepG2 cells exhibited the highest basal level of autophagy and TRAP1 expression with medium invasive ability." (PMID 38098505, 2023). "It was found that the efficacy of an SDH targeting drug (mitocans) for liver cancer treatment could be improved by increasing S-nitrosylation of mitochondrial chaperone TNF receptor associated protein 1 (TRAP1) at Cys50 by inhibiting a denitrosylase GSNOR." (PMID 33925645, 2021). "In liver cancer cells, TRAP1 knockdown prevented invasion, migration, and proliferation; increased reactive oxygen species; and promoted apoptosis." (PMID 41422190, 2025). "Treatment with rapamycin also greatly increased autophagy in the 4 liver cancer cell lines and enhanced the expression of TRAP1 in HepG2, Hep3B2.1-7 and Sk-hep1 cells." (PMID 38098505, 2023). "Thus, TRAP1, particularly in liver cancer, represents a highly promising prognostic biomarker and a novel metabolic therapeutic target." (PMID 41422190, 2025). "Therefore, TRAP1 may be related to autophagy in liver cancer, as cell invasiveness, HBV infection and autophagy induction have different effects on TRAP1 expression." (PMID 38098505, 2023).
neuroblastoma (3 papers, 2012 to 2023). Neuroblastoma (NB) is the most common solid, extracranial childhood tumor. "However, others have demonstrated that TRAP1 expression is up-regulated following treatment with H2O2 (300 μM) for 24 h in a neuroblastoma cell line (SH-SY5Y)." (PMID 36829938, 2023).
prostate adenocarcinoma (3 papers, 2015 to 2022). "The compensatory increased recruitment of Hsp90 to mitochondria was also observed in TRAP1-knockout mice as well as in TRAP-1-silencing prostate adenocarcinoma PC3 cells." (PMID 26517089, 2015). "Furthermore, TRAP1 transgenic mice exhibited higher incidence of prostatic adenocarcinoma with elevated cell proliferation and reduced apoptosis while TRAP1 silencing hindered prostatic tumorigenesis in Pten+/− mice." (PMID 31426412, 2019).
serous ovarian cancers (3 papers, 2018 to 2022). "In keeping with patient data, platinum resistant cell lines show lower TRAP1 levels than their sensitive counterparts in cellular models of high grade serous ovarian cancer isogenic matched paired cell lines derived from the same patient before and after platinum-based therapy." (PMID 29621137, 2018). "Interestingly, several complex III components and assembly factors show an inverse correlation with survival and response to platinum-based therapy in high grade serous ovarian cancers, where TRAP1 inversely correlates with stage and grade and directly correlates with survival." (PMID 36510251, 2022). "In addition, we also show that other complex III components are upregulated in the late stages of human high grade serous ovarian cancers (HGSOCs), in which TRAP1 is downmodulated, and identify the assembly factor TTC19 as a novel biomarker of potential clinical interest in this tumor type." (PMID 36510251, 2022). "Moreover, in high-grade serous ovarian cancers, TRAP1 expression is mainly found in peritoneal biopsies distant from the primary tumors, suggesting that low TRAP1 expressing cancers may be more prone to spread from the primary site." (PMID 29621137, 2018).
adenoma (2 papers, 2017 to 2024). A neoplasm arising from the epithelium. "It is intriguing that TRAP1 upregulation occurs at early stages of colorectal tumorigenesis, being already evident in high-grade adenomas and in in situ carcinomas." (PMID 28177905, 2017). "TRAP1 levels were overexpressed independently from stages of disease (p < 0.05) and this is consistent with our previous observation that TRAP1 upregulation is an early event in colorectal carcinogenesis occurring at the transition between low- and high-grade adenomas." (PMID 39210159, 2024). "Interestingly, TRAP1 is upregulated at the transition between low- and high-grade adenomas, being the latter characterized by increased levels of TRAP1 in 4/6 cases and is upregulated in 7/11 in situ carcinomas." (PMID 28177905, 2017).
amyotrophic lateral sclerosis (2 papers, 2022 to 2023). Amyotrophic lateral sclerosis (ALS) is a neurodegenerative disease characterized by progressive muscular paralysis reflecting degeneration of motor neurons in the primary motor cortex, corticospinal tracts, brainstem and spinal cord. "Here we show that overexpression of TRAP1 protects motor neurons from mitochondrial dysfunction and death induced by exposure to oxidative stress conditions modelling amyotrophic lateral sclerosis (ALS)." (PMID 35163711, 2022).